PGR (progesterone receptor)
Diseases named in the same sentence as PGR in open-access papers (continued):
Sharing a sentence is not in itself a finding about the gene and the disease.
breast cancer (continued). "Patients with previously untreated HER-2 negative operable breast cancer not eligible for neo(adjuvant) treatment were divided into two cohorts, i.e., group A: histologically proven ER+ and/or PgR+ and group B: ER−/PgR− breast cancer (i.e., TNBC)." (PMID 30788286, 2019). "The luminal breast cancer subtype, which express estrogen receptor (ER) and/or progesterone receptor (PR) in the tumor cells, comprise the largest subgroup, accounting for approximately 75% of all breast cancers." (PMID 31801490, 2019). "Our results show that Ki-67 has prognostic value for recurrence and survival in patients with ER-positive and HER2-negative early breast cancer only in the context of low PgR expression level." (PMID 31975992, 2019). "Another study analysed both nuclear and cytoplasmic expression (n = 32) on IHC in early operable primary breast cancer with ER and PgR positive expression." (PMID 30696074, 2019). "Breast cancer is currently classified into five intrinsic subtypes, typically using immunohistological markers (estrogen receptor [ER], progesterone receptor [PR], HER2 gene, and/or ERBB2 protein status), tumor grade, and/or proliferation." (PMID 31315058, 2019). "For postmenopausal women, several meta-analyses have consistently shown positive associations among high adiposity, adult weight gain, and risk of hormone receptor-positive (estrogen receptor-positive/ER+ and progesterone receptor-positive/PR+) breast cancer." (PMID 31555578, 2019). "In this article, breast cancer was classified into five subtypes based on immunohistochemistry (IHC) markers which include estrogen receptor (ER), progesterone receptor (PR) and human epidermal growth factor receptor 2 (HER2)." (PMID 30866472, 2019). "Breast cancer subtypes can be characterised by the expression profiles of key signalling receptors (ERα, PgR, HER2 and EGFR)." (PMID 30987655, 2019). "The histological evaluation of estrogen receptor (ER) and progesterone receptor (PR) expression in breast cancer lesions from biopsy tissue can stratify patients to receive endocrine therapy." (PMID 31659497, 2019). "This cohort of breast cancer patients was previously investigated for HCMV protein expression and association with estrogen receptor-alpha (ER) and progesterone receptor (PGR) expression and the results were reported earlier." (PMID 31203442, 2019). "Expressions of estrogen receptor 1 (ESR1), progesterone receptor (PGR), and human epidermal growth factor receptor type 2 (HER2) are deficient in triple-negative breast cancer (TNBC) breast cancer." (PMID 31409331, 2019). "Approximately 75% of all new breast cancers are luminal breast cancer subtypes, which express estrogen receptor (ER) and/or progesterone receptor (PR)." (PMID 31703648, 2019). "Phosphorylation of Ser294 in a progesterone receptor is a common event in breast cancer progression, required to maintain stem cell fate in breast cancer." (PMID 31114446, 2019). "In breast cancer, four subtypes have been identified based on the hormone receptors (HR) [estrogen receptor (ER), progesterone receptor (PR)] and Human Epidermal growth factor Receptor-2 (HER2)." (PMID 30972613, 2019). "To identify the potential mechanisms leading JEKHT to increase sensitivity to TAM, we first measured protein levels of ERα, ERβ and PgR in the mammary tumors." (PMID 30640711, 2019). "Molecular classification of breast cancer relies on the expression of estrogen receptor (ER), progesterone receptor (PR) and human epidermal growth factor receptor-2 (HER-2)." (PMID 31481958, 2019). "Breast cancer therapy mainly targets the estrogen receptor (ER), the progesterone receptor (PR) or human epidermal growth factor receptor 2 (HER-2)." (PMID 31069012, 2019). "We found that knowing Ago2 protein levels in tumour improves the ability to predict breast cancer subtype (by 20%), which is related Ago2 staining improving the ability to predict Estrogen or Progesterone receptor status (by 15.7 and 17.5% respectively)." (PMID 31324173, 2019).
breast cancer (continued). "Triple negative (TN) breast cancer is a particular type of breast cancer, which lacks the expression of oestrogen receptor (ER), progesterone receptor (PgR), and ERBB2." (PMID 31341911, 2019). "Breast cancer is classified into three major therapeutic subtypes: estrogen and/or progesterone receptor-positive (ER+, PR+), HER2+, and triple-negative breast cancer (TNBC) (lacking expression of ER, PR, and HER2)." (PMID 31665136, 2019). "To assess the effectiveness of our deconvolution, we first examined the three receptor genes associated with molecular subtypes of breast cancer: the oestrogen receptor (ESR1), progesterone receptor (PGR), and human epidermal growth factor receptor 2 (ERBB2)." (PMID 31308365, 2019). "Historically, breast cancers have been classified based on the expression of several cell-surface receptors, namely the estrogen receptor (ER), progesterone receptor (PR), and human epidermal growth factor receptor 2 (HER2)." (PMID 31921847, 2019). "Estrogen receptor-α (ERα) and progesterone receptor (PR) are expressed in most human breast cancers and are important therapeutic targets." (PMID 31598114, 2019). "Ki-67 had a value as a prognostic factor only under low PgR expression level in early breast cancer." (PMID 31975992, 2019). "These microarray signatures lead to the stratification of breast cancer patients based on their level of expression of estrogen receptor alpha (ERα), progesterone receptor (PR), or the human epidermal growth factor receptor 2; ERBB2 (HER2)." (PMID 31817827, 2019). "Triple-negative breast cancers (TNBCs) represent approximately 10–15% of all breast cancers and are a highly aggressive subtype of tumors that lack estrogen receptor (ER), progesterone receptor (PR) and HER2 gene amplification." (PMID 31748508, 2019). "The subtypes of breast cancer are classified based on the expression of the oestrogen receptor (ER), progesterone receptor (PR) and HER2." (PMID 31728117, 2019). "Recently, the most effective treatment for breast cancer has been based on an abnormal oncogene of the cancer cells, while the expressions of the estrogen receptor (ER) and progesterone receptor (PR) are used as prognostic factors." (PMID 31772936, 2019). "This particularly aggressive cancer subtype represents 10–20% of breast cancer cases and is characterized by the low expression of estrogen receptor (ER), progesterone receptor (PR) and HER2 receptor." (PMID 31007848, 2019). "Treatment of breast cancer patients depends upon factors such as presence of estrogen receptor, progesterone receptor or HER2 overexpression." (PMID 31578396, 2019). "Breast cancer is a heterogeneous group of tumors with different estrogen receptor (ER)/progesterone receptor (PR)/human epidermal growth factor receptor 2 (HER2) statuses." (PMID 31601781, 2019). "Of note, established biomarkers in breast cancer such as oestrogen receptor, progesterone receptor and HER2 are used in clinical decision-making." (PMID 31426778, 2019). "Polarization toward the M2 phenotype showed strong correlation with the aggressiveness of breast cancer characterized by higher histologic grade, higher Ki-67 proliferating index, estrogen receptor and progesterone receptor negativity." (PMID 32039007, 2019). "Among the 9844 patients, the largest series in Japan, 27 (0.3%) were initially diagnosed as ER−/PgR+ breast carcinomas and we re-evaluated by IHC." (PMID 30066060, 2019). "Breast cancer (BC) intrinsic subtype classification is based on the expression of estrogen receptor (ER), progesterone receptor (PR), human epidermal growth factor receptor 2 (HER2), and proliferation marker Ki-67." (PMID 30915533, 2019). "It is generally suggested that all pathological diagnosed primary breast carcinomas be examined for oestrogen receptor (ER) and progesterone receptor (PgR) protein expression by immunohistochemical staining (IHC)." (PMID 30066060, 2019).
breast cancer (continued). "The aim of our study was to determine the existence of the ER−/PgR+ breast carcinoma phenotype and, if found, to elucidate its clinicopathological features and discuss management." (PMID 30066060, 2019). "Progesterone-Receptor (PR) positivity is related with an enhanced response to breast cancer therapy, conversely cyclin D1 (CD1) is a retained marker of poor outcome." (PMID 31426542, 2019). "Immunostaining of several tumors revealed that the Nf1 mammary tumors were positive for estrogen receptor, progesterone receptor, and HER2/Neu receptor and highly proliferative based on Ki67 staining." (PMID 30182054, 2018). "Luminal A breast cancer defined as ER and PgR positive with a low Ki67 index has been proven to have an excellent prognosis." (PMID 29928479, 2018). "We also added genes important for breast cancer biology or subtyping (ER, PGR, ERBB2, MKI67, AURKA and FOXC1)." (PMID 29973242, 2018). "Among all the breast cancer cases, 15% are triple-negative breast cancers (TNBCs), which lack expression of estrogen receptor (ER), progesterone receptor (PR), and human epidermal growth factor receptor 2 (HER2) and have a very aggressive disease course." (PMID 29702405, 2018). "Progesterone, a ligand for progesterone receptor, is reported to have anti-proliferative function in PR-positive breast cancers in vivo and in vitro." (PMID 29535312, 2018). "Breast cancers (BCas) that lack expression of the estrogen receptor (ER), progesterone receptor (PR), and human epidermal growth factor receptor 2 (HER2) are referred to as triple negative breast cancers (TNBCs) and have the poorest clinical outcome." (PMID 30100993, 2018). "In this study, luminal breast cancer was subtyped using PgR and Ki67 index of established cut-off values, 20% and 14%, respectively." (PMID 29928479, 2018). "Conversely, PgR-related signaling pathways are critically involved in the maintenance of breast cancer phenotypes." (PMID 30080878, 2018). "The beneficial effects of lignans in this study were limited to ER+ breast cancer and progesterone receptor positive." (PMID 29468163, 2018). "The main prognostic biomarkers in early-stage breast cancer are tumor size, grade, lymph node status, number of positive lymph nodes, estrogen and progesterone receptor (ER, PgR) status and epidermal growth factor receptor 2 (HER2) status." (PMID 30063723, 2018). "Luminal breast cancer, defined as hormone receptor-positive and HER2 negative breast cancer, is clinically divided into luminal A and luminal B breast cancer using PgR and Ki67 index." (PMID 29928479, 2018). "RT-qPCR also can be used for the determination of breast cancer molecular subtype by quantification of ER and PGR mRNA levels." (PMID 29986702, 2018). "Testing for estrogen receptor (ER) and progesterone receptor (PR) markers has been recommended for all newly diagnosed breast cancer patients by the College of American Pathologists and American Society of Clinical Oncology." (PMID 30558615, 2018). "Recent advances in cancer genomics mapping has helped to classify breast cancer based on the expression of cellular receptors, which are estrogen receptor (ER), progesterone receptor, and anti-human epidermal growth factor receptor 2 (HER2)." (PMID 29374471, 2018). "Therapeutic decisions in breast cancer patients crucially depend on the status of estrogen receptor, progesterone receptor and HER2, obtained by immunohistochemistry (IHC)." (PMID 30117066, 2018). "The routinely used biomarkers of breast cancer are estrogen receptor (ER), progesterone receptor (PgR) and human epidermal growth factor receptor 2 (HER2)." (PMID 29793439, 2018).
breast cancer (continued). "Recent pre-clinical studies indicate that activated progesterone receptor (PR) (particularly the PR-B isoform) binds to oestrogen receptor-α (ER) and reprogrammes transcription toward better breast cancer outcomes." (PMID 30410061, 2018). "The majority had early stage (85.3%) and estrogen and/or progesterone receptor positive (84.6%) breast cancer." (PMID 29378534, 2018). "The molecular classification of breast cancer, based on the expression of estrogen/progesterone receptor (ER/PR) and epidermal growth factor receptor 2 (HER2), provides different prognostic/predictive implications and therapeutic informations." (PMID 30018736, 2018). "In the context of early-stage, ER/PgR-positive breast cancer, adjuvant chemotherapy is only effective in a small subgroup of patients with a high risk of relapse." (PMID 29304138, 2018). "A diagnosis of primary breast cancer (solid tubular carcinoma) was made; estrogen receptor (EgR) and progesterone receptor (PgR) were positive, and human epidermal growth factor receptor 2 (HER2) was negative." (PMID 29580267, 2018). "The risk of breast cancer related to CD44 polymorphism was further examined with stratification by age, family history of breast cancer, pathological type, clinical stage, estrogen/progesterone receptor status (ER, PR), and Her2 expression." (PMID 29483847, 2018). "AKT also reduces PGR expression levels in breast cancer cells, endometrial cancer cells, and uterine stromal cells affected by endometriosis." (PMID 29843645, 2018). "We examined intrinsic subtypes of breast cancer in BRCA1/2 mutation carriers based on the information about their ER, PgR, and HER2 status." (PMID 29176636, 2018). "Black Americans with breast cancer were reported to have differences in progesterone receptor genes." (PMID 29506526, 2018). "Traditionally, estrogen receptor (ER), progesterone receptor (PR) and Her2 have been used to classify breast cancer into three subtypes: positive for hormonal receptors (ER+), Her2+, and triple negative (TNBC) without these receptors." (PMID 30279960, 2018). "Treatment decisions for breast cancer are significantly influenced by subtype, which is determined from expression of estrogen receptor (ER), progesterone receptor (PgR), human epidermal growth factor receptor 2 (HER2), and the proliferation marker Ki67." (PMID 29304138, 2018). "We found that ERα signaling is not only sustained in breast cancer PDEs, but that the estrogenic response of ERα‐positive PDEs significantly varies in terms of PGR regulation." (PMID 30117261, 2018). "In the clinical setting, HER2 is used as a typical biological marker, along with the estrogen receptor (ER) and progesterone receptor (PR), to diagnose the breast cancer." (PMID 30229394, 2018). "Determination of the therapeutic strategy for breast cancer depends on the expression patterns of ERα, progesterone receptor, and human epidermal growth factor receptor 2 (HER 2) in needle biopsy samples." (PMID 29360794, 2018). "Triple-negative breast cancer (TNBC) is a diagnosis of exclusion, encompassing all breast cancers which lack expression of the estrogen receptor (ER) and progesterone receptor (PR), and lack amplification of the human epidermal growth factor receptor 2 (HER2)." (PMID 30352973, 2018). "Breast cancer is divided into several distinct subtypes, and the expression level of estrogen receptor (ER), progesterone receptor (PgR), and human epidermal growth factor receptor 2 (HER2) is fundamental for treatment decision and prognosis of the disease." (PMID 30133130, 2018). "Additional expression of PGR in ERα-positive breast cancer cells has suppressed estrogen-mediated proliferation and transcriptional activity of ERα." (PMID 30344242, 2018). "We previously showed the value of PgR and Ki67 to predict benefit from first-line endocrine therapy in a case series of patients with advanced luminal breast cancer." (PMID 29587674, 2018).
breast cancer (continued). "Three markers aberrantly expressed in breast cancer are used for targeted therapy in clinics, including the hormone receptors for estrogen (ER) and progesterone (PgR) and the human epidermal growth factor receptor 2 (Her2)." (PMID 30473665, 2018). "Currently, the classification of breast cancer is based mainly on the expression of the estrogen receptor (ER), progesterone receptor (PgR), and the overexpression or amplification of human epidermal growth factor receptor 2 (HER2/c-ErbB2)." (PMID 30347895, 2018). "Triple-negative breast cancer (TNBC) is a type of breast cancer that lacks the expression of estrogen receptor (ER), progesterone receptor (PgR) and human epidermal growth factor receptor-2 (HER2)." (PMID 30241470, 2018). "Routine breast cancer case showed an expression of three distinctive receptors which are oestrogen receptor (ER), progesterone receptor (PR) and human epidermal growth factor 2 receptor (Her2)." (PMID 29281924, 2018). "Breast cancers are well known as heterogeneous diseases, which can be sub-classified by the presence of estrogen receptor (ER), progesterone receptor (PR), and HER2/neu receptor." (PMID 29713393, 2018). "Preoperative progesterone intervention has been shown to confer a survival benefit to breast cancer patients independently of their progesterone receptor (PR) status." (PMID 30337371, 2018). "Breast cancers are divided into several different subtypes according to the expression of three receptors: estrogen receptor (ER), progesterone receptor (PR), and human epidermal receptor 2 (HER2)." (PMID 30052635, 2018). "Characteristically, PGR (progesterone receptor) is repressed in luminal B breast cancer and there is enhanced resistance to endocrine therapies." (PMID 29881724, 2018). "Endocrine therapies—namely, tamoxifen and aromatase inhibitors—reduce the risk of reoccurrence of breast cancer in patients diagnosed as having oestrogen receptor and/or progesterone receptor positive breast cancer following surgery (adjuvant treatment)." (PMID 30297439, 2018). "Breast cancer is a heterogeneous disease with 3 established immunohistochemical biomarkers: Estrogen Receptor (ER), progesterone receptor (PR) and HER2 (human epidermal growth factor 2) receptor." (PMID 29463223, 2018). "Treatment of metastatic breast cancer, as well as early-stage breast cancer, is based on the status of estrogen receptor (ER), progesterone receptor (PR), and epidermal growth factor receptor 2 (HER2)." (PMID 29464068, 2018). "Breast cancer can be divided into three biologic subtypes, based on biomarkers such as the estrogen receptor (ER), progesterone receptor (PR), and human epidermal growth receptor 2 (HER2)." (PMID 29967409, 2018). "Its function in breast cancer development, however, remains unestablished, although the theory of an individual contribution by the PGR isoforms to malignant development is receiving attention." (PMID 30054508, 2018). "Altogether, these results further reveal that both CCND1 and PGR are involved in mediating the anti-breast cancer effects of TAM in ER+-breast cancer tissue." (PMID 29416786, 2018). "Breast cancers are generally classified based on their hormone receptor status, namely, estrogen receptor (ER), progesterone receptor (PR), and human epidermal growth factor receptor 2 (HER2)." (PMID 30524959, 2018). "In this current study, we focus on molecular profiling in advanced breast cancers beyond standard estrogen receptor (ER), progesterone receptor (PR), and HER2 testing." (PMID 29177603, 2018). "All further experiments were conducted with the breast cancer cell line MCF-7, presenting the most common breast cancer subtype (positive for estrogen and progesterone receptor expression)." (PMID 30337557, 2018). "Breast cancer (BC) is a heterogeneous disease, yet clinical management is based on only three biomarkers: estrogen receptor (ER), progesterone receptor (PR) and the human epidermal growth factor receptor (HER2)." (PMID 30572639, 2018).